RNU6-1201P (RNA, U6 small nuclear 1201, pseudogene)
Gene: Small nuclear RNA gene on chromosome 17 (48,088,678 to 48,088,784, reverse strand). Ensembl gene ENSG00000206954.
Homologues: Orthologues: chimpanzee U6 (99% identical), guinea pig U6 (88% identical), mouse Gm25812 (84% identical). Paralogues in human: RNU6-116P (91% identical), RNU6-1011P (90% identical), RNU6-10P (90% identical), RNU6-12P (90% identical), RNU6-13P (90% identical), RNU6-32P (90% identical), RNU6-33P (90% identical), RNU6-41P (90% identical), RNU6-45P (90% identical), RNU6-47P (90% identical), RNU6-1 (89% identical), RNU6-1060P (89% identical), and 1285 more.